TERT (telomerase reverse transcriptase)
Diseases named in the same sentence as TERT in open-access papers (continued):
Sharing a sentence is not in itself a finding about the gene and the disease.
papillary thyroid carcinoma (continued). "As BRAF, TERT, HLA-G, and microRNAs have been individually associated with papillary thyroid carcinoma (PTC), we aimed to evaluate the individual and collaborative role of these markers in PTC in the same patient cohort." (PMID 37569841, 2023). "Age at diagnosis (AAD) and telomerase reverse transcriptase (TERT) promoter mutations are prognostic factors in differentiated thyroid carcinoma (DTC), and the prevalence of the mutations increases with AAD." (PMID 37948420, 2023). "All five nodules harbouring the BRAF V600E mutation were malignant carcinomas, including three classic papillary thyroid carcinomas, one follicular variant papillary carcinoma and one anaplastic thyroid carcinoma concurrent with TERT mutation." (PMID 35247035, 2022). "TERT promoter mutation has recently emerged as a promising prognostic biomarker for aggressive papillary thyroid cancer (PTC), along with BRAF B600E mutation." (PMID 36230856, 2022). "B-Raf proto-oncogene, serine/threonine kinase (BRAFV600E), and telomerase reverse transcriptase (TERT) promoter mutations were the most frequently identified in papillary thyroid carcinoma." (PMID 35992139, 2022). "The aim of this study is to investigate the effects of the functional TERT rs2736100 genetic polymorphism on the outcomes of papillary thyroid carcinoma (PTC) patients." (PMID 36704521, 2022). "Some authors have also suggested the role of NRAS exon 61 mutation in the progression of PDTC from well-differentiated thyroid carcinoma and TERT-p mutations as the most common alterations in PDTC." (PMID 35892838, 2022). "The prevalence of TERT promoter mutation increases in the order of differentiated thyroid carcinoma, PDTCs, and ATCs." (PMID 33672707, 2021). "TERT promoter mutation was described in 40% of the ATC cases and papillary carcinomas that carry a TERT promoter mutation are more likely to transform to ATC." (PMID 32591993, 2020). "This study aimed to evaluate the association between TERT promoter mutations and clinical behaviors (including clinicopathological features and prognosis) in differentiated thyroid carcinomas (DTC)." (PMID 31655978, 2020). "The role of telomerase reverse transcriptase (TERT) gene promoter mutations in the aggressiveness of papillary thyroid cancer (PTC) remains to be further investigated." (PMID 26943032, 2016). "We performed a meta-analysis to elucidate the associations of the clinicopathological characteristics and prognostic factors of papillary thyroid cancer (PTC) with TERT promoter mutations." (PMID 27833153, 2016). "The BRAF V600E and telomerase reverse transcriptase (TERT) promoter mutations have been reported in papillary thyroid carcinoma (PTC)." (PMID 27064992, 2016). "TERT promoter mutations have been associated with adverse prognosis in papillary thyroid carcinomas (PTCs)." (PMID 26667986, 2016). "In well-differentiated thyroid carcinoma, TERT promoter mutations are detected infrequently." (PMID 39744583, 2025). "However, they were unable to confirm previous observations in papillary thyroid carcinomas regarding the relationship between 5hmC loss and TERT mutations." (PMID 38285158, 2024). "viii.TERT promoter mutations are more frequent and have higher mutated allelic fraction in poorly differentiated, anaplastic, and aggressive/advanced cancers (including high-grade papillary carcinoma) compared with well-differentiated carcinoma." (PMID 38108848, 2024). "The literature proposes that the occurrence of PIK3CA mutations may be less useful than TERT promoter mutations for assessing the risk of anaplastic transformation in papillary carcinoma." (PMID 36672362, 2023). "A mutation of TERT promoter was found in about 7.5% of PTCs, which induced the abnormal activation of telomerase is closely related to the invasive clinical behavior of papillary carcinoma." (PMID 32477264, 2020).
papillary thyroid carcinoma (continued). "TERT promoter (TERTp) mutations are important factors in papillary thyroid carcinomas (PTCs)." (PMID 30200646, 2018). "Besides, the incorporation of molecular markers, such as BRAF, RAS and TERT detection, enhances the diagnostic value of thyroid nodules exhibiting indeterminate cytology, and plays a role in predicting outcomes for patients with papillary thyroid carcinoma." (PMID 40510463, 2025). "Aggressive/advanced papillary carcinomas, many of which are histologically high-grade, have at least one of three genetic alterations: duplication of chromosome 1q, duplication of chromosome 5 p harboring the TERT genomic locus, and TERT promoter mutation (THYT1 signature)." (PMID 38108848, 2024). "Previous studies have found a significant correlation between TERT promoter mutations and distant metastases, higher pathological stage, disease recurrence, disease-specific mortality, and other adverse prognostic features in 647 differentiated thyroid carcinoma lesions, especially in PTC." (PMID 38562417, 2024). "Indeed, previous studies indicate that both TERT promoter mutations and TERT mRNA expression indicate worse clinical outcome in differentiated thyroid carcinoma and may also be associated to higher Ki-67 indices." (PMID 35305239, 2022). "Aggressive/advanced papillary carcinomas, many of which are histologically high grade, have at last one of three genetic alterations: duplication of chromosome 1q, duplication of chromosome 5p harboring the TERT genomic locus and TERT promoter mutation (THYT1 signature)." (PMID 33543394, 2021). "Out of the 11 cases of gene fusion patients with papillary thyroid carcinoma, only one case showed a combination of ETV6-NTRK3 fusion and TERT mutation." (PMID 38607456, 2024). "Telomerase reverse transcriptase (TERT) promoter mutation has been investigated for its clinical and prognostic significance in aggressive papillary thyroid cancer (PTC)." (PMID 36230856, 2022). "At the time of diagnosis the patient had a papillary thyroid cancer that already carried a BRAF(V600) and a TERT promoter mutation." (PMID 32591993, 2020). "Clinical-pathological characteristics according to the status of BRAF, RAS, and TERT mutations and RET rearrangements in papillary thyroid carcinomas." (PMID 32425887, 2020). "DNA extracted from 100 thyroid tumors (10 follicular adenomas, 10 follicular cancers, 5 medullary cancers, and 75 papillary thyroid cancer (PTC) were used for detection of BRAF and TERT mutations." (PMID 31810221, 2019). "This study is to investigate if any relationship exists between the telomerase reverse transcriptase (TERT) promoter or proto-oncogene BRAF mutation and ultrasound (US) and clinicopathological features of papillary thyroid carcinomas (PTCs)." (PMID 29312581, 2017). "Especially, mutations of the TERT promoter, RET, and BRAF are established as major prognostic biomarkers and are associated with clinical aggressiveness of papillary thyroid carcinoma." (PMID 29108240, 2017).
papillary thyroid carcinoma (continued). "Notably, substantial correlations have been identified between BRAF V600E and TERT promoter genetic changes, with especially frequent simultaneous presence detected in papillary thyroid carcinomas and skin melanomas." (PMID 40469184, 2025). "Several research has focused on molecular mutations, notably TERT promoter mutation and BRAFV600E, in the context of radioiodine-refractory differentiated thyroid carcinoma (DTC), offering critical insights into the genetic mechanisms driving treatment resistance." (PMID 40241101, 2025). "Therefore, our aim was to examine the role of TERT expression level alterations using RNAscope®, and histological patterns in a cohort of papillary thyroid carcinoma patients with a tumor size ≤ 1 cm harboring synchronous lymph node metastasis." (PMID 38616265, 2024). "Telomerase reverse transcriptase (TERT) has been reported in papillary thyroid carcinoma (PTC)." (PMID 38562417, 2024). "The study supported the risk stratification of papillary thyroid carcinomas into three subgroups based on BRAF V600E and TERT promoter mutation positivity, with increasing aggressiveness from dual negativity, positivity in either mutation alone, to dual positivity." (PMID 34702207, 2021). "Molecular re-examination of the primary follicular variant papillary thyroid carcinoma demonstrated a codon 600 BRAF mutation and a TERT promoter wildtype sequence, while the primary TCV-PTC was positive for mutations in both codon 600 of BRAF as well as the TERT promoter." (PMID 33466206, 2021). "Human telomerase reverse transcriptase (TERT) expression has demonstrated prognostic value for predicting recurrence in papillary thyroid carcinomas, and TERT has been found to be overexpressed in the right colon compared to the left, indicating worse prognosis in CRC." (PMID 32596958, 2020). "Both papillary thyroid carcinoma and right colon cancer are characterized by BRAF V600E mutation, which might interact with TERT expression and TERT mutation for the promotion of tumour invasion." (PMID 32596958, 2020). "In Chinese patients with papillary carcinoma, TERT promoter mutations rather than BRAF V600E mutations were associated with a more advanced TNM stage and shorter progression-free survival." (PMID 29108240, 2017). "In one of the tumors with accompanying lymph node metastases from squamous cell carcinoma, TERT expression was observed in squamous cell carcinoma in the basal portion of the tumor while being absent in superficial cell layers, as well as in the metastasis of papillary thyroid carcinomas." (PMID 38616265, 2024). "Mutations of the v-Raf murine sarcoma viral oncogene homolog B (BRAF) oncogene and telomerase reverse transcriptase (TERT) promoter region are indicators of poor prognosis in papillary thyroid carcinoma (PTC) and might predict future occurrences of distant metastases." (PMID 33466206, 2021). "However, in an analysis of papillary thyroid cancers and TCGA data, an inverse relationship was found between GABPA expression and TERT expression in TERT promoter mutant tumors, highlighting the need for further study of TERT mutation activation." (PMID 32849278, 2020). "The association between clinicopathological variables, including age-TERT interaction and cancer-specific survival (CSS), in patients with differentiated thyroid cancer (DTC)." (PMID 37948420, 2023). "Recurrent papillary carcinomas with anaplastic transformation showcase a higher prevalence of BRAFV600E mutation and TERT promoter mutation compared with those without anaplastic transformation." (PMID 40271195, 2025).
papillary thyroid carcinoma (continued). "Taken together, our data indicate that TERT expression level alterations are not involved in the development of early lymph node metastasis in patients with sub-centimetric papillary thyroid carcinomas." (PMID 38616265, 2024). "In a study, TERT promoter mutations were absent in 60 follicular adenomas and in 16 NIFTP cases, but present in 3 of 83 papillary carcinomas, follicular variant, and in 3 of 29 cases of minimally invasive follicular carcinomas." (PMID 33543394, 2021).
neuroblastoma (71 papers, 2016 to 2026). Neuroblastoma (NB) is the most common solid, extracranial childhood tumor. "The higher temporal and spatial resolutions of TERT breakpoint detection reported supports this assay’s potential in future management protocols for patients with very high-risk TERT-rearranged neuroblastomas." (PMID 39760332, 2025). "Approximately 30% of newly diagnosed high-risk neuroblastomas have high TERT transcript levels and active telomerase caused by genomic TERT rearrangements." (PMID 39760332, 2025). "In another 23%-31% of high-risk neuroblastomas, TERT is activated through proximal chromosomal rearrangements, which induces its transcriptional upregulation." (PMID 40115016, 2025). "Real-time molecular monitoring of TERT-rearranged high-risk neuroblastoma is an unmet clinical need." (PMID 39760332, 2025). "We next applied our developed ddPCR assay protocol to assess breakpoints specific to the TERT-rearranged high-risk neuroblastoma diagnosed in patient P1 by TERT break-apart FISH and hybrid capture–based panel sequencing." (PMID 39760332, 2025). "We conclude that multiplexing markers will provide optimal disease surveillance for patients treated for very high–risk neuroblastoma, as performed for patient P3 by combining TERT breakpoint and ALK p.R1275Q marker surveillance in ctDNA." (PMID 39760332, 2025). "To assess the power of our ddPCR assay for longitudinal monitoring of TERT breakpoints in patient samples, we analyzed tumor, blood, and BM samples from three patients with TERT-rearranged high-risk neuroblastoma (P2, P3, and P4)." (PMID 39760332, 2025). "Telomerase is reactivated by genomic TERT rearrangements in ∼30% of diagnosed high-risk neuroblastomas." (PMID 39760332, 2025). "As yet, no molecular assays accurately detecting, and quantifying MRD exist for the neuroblastoma high-risk subgroup molecularly defined by the presence of TERT aberrations." (PMID 39760332, 2025). "MYCN amplification is present in nearly 40% of high-risk neuroblastomas and is associated with upregulated expression of TERT and telomere dysfunction." (PMID 40115016, 2025). "Second, in a subset of high-risk neuroblastoma cases, rearrangement of the TERT locus on chromosome 5 results in a juxtaposition of a proximal enhancer and TERT that consequently induces a high level of TERT expression, a process termed “enhancer hijacking”." (PMID 38837897, 2024). "Taken together, these data suggest that telomerase-independent cancer cells with long telomeres are associated with repressed TERT expression and hypomethylation of the TERT locus in neuroblastoma." (PMID 38837897, 2024). "Chromosome rearrangements at the TERT locus have been linked in several studies to the development of neuroblastoma." (PMID 38819232, 2024). "Altogether, these data contextualize the epigenetic regulation of the TERT locus in high-risk neuroblastoma based on differing telomere maintenance mechanisms." (PMID 38837897, 2024). "Telomere maintenance in neuroblastoma is linked to poor outcome and caused by either telomerase reverse transcriptase (TERT) activation or through alternative lengthening of telomeres (ALT)." (PMID 39635126, 2024). "Acquiring a telomere maintenance mechanism is a hallmark of high-risk neuroblastoma and commonly occurs by expressing telomerase (TERT)." (PMID 38837897, 2024). "Elevated TERT expression is strongly associated with TERT promoter rearrangements or MYCN-amplification in neuroblastoma." (PMID 35406427, 2022). "TERT gene expression has also been linked to methylation of the specific CpG site cg11625005 (chr5:1,295,737 in hg19) in the TERT promoter in neuroblastoma and other tumour types." (PMID 36175618, 2022).